IL10 (interleukin 10)
Diseases named in the same sentence as IL10 in open-access papers (continued):
Sharing a sentence is not in itself a finding about the gene and the disease.
autoimmune disease (continued). "Conversely, IL-10 is predominantly regarded as an antiinflammatory cytokine, but its role in autoimmune disease remains ambiguous, as illustrated by the failure of inducing an autoimmune syndrome in IL-10–deficient mice." (PMID 38226621, 2024). "Conversely, other studies have shown that MSCs decrease levels of IL-1β, IL-17α, and IL-6 while increasing IL-10 levels in various autoimmune diseases." (PMID 39273184, 2024). "Alterations in the number of different circulating Breg subsets and impairment in the ability to secrete IL-10 have been shown in autoimmune diseases (e.g. systemic lupus erythematosus, rheumatoid arthritis, and multiple sclerosis)." (PMID 38134245, 2024). "Genetic variations in interleukin-10 (IL10) and interleukin-6 receptor protein (IL6R) genes are identified to be associated with autoimmune disorders." (PMID 38822340, 2024). "Inhibition of FABP5 triggers activation of the cGAS‐STING pathway, inducing IL‐10 production and promoting the inhibitory activity of Treg, thus attenuating autoimmune disorders." (PMID 38500390, 2024). "In future work, it will be important to describe IL-10-producing B cells, such as CD138+ Bregs (IL-10+CD138+) or IL-10-producing plasma cells, which have been ascribed to exert regulatory functions in autoimmune inflammation and other autoimmune diseases." (PMID 39324141, 2024). "Later studies established the role of IL-10-producing Bregs in immune suppression and maintenance of tolerance, typically impaired in autoimmune diseases." (PMID 39346706, 2024). "Understanding the regulatory mechanisms governing IL10 expression is essential for elucidating the pathophysiology of autoimmune diseases and identifying potential therapeutic targets." (PMID 39337678, 2024). "IL-10, an anti-inflammatory cytokine, has been demonstrated to be involved in autoimmune diseases such as systemic lupus erythematosus and multiple sclerosis." (PMID 38310292, 2024). "Since IL-10 is a key anti-inflammatory cytokine for the suppression of autoimmune diseases like MS, it is likely that IL-10 plays a role in the p40 monomer-mediated protection of EAE." (PMID 38435456, 2024). "Human recombinant IL-10 can be used to mitigate inflammatory responses in various conditions, including autoimmune diseases and inflammatory disorders." (PMID 38248028, 2024). "Because MaR1 promotes the expression and production of IL10, which can influence Th17 pathogenicity in autoimmune disorders, we next investigated the immune cells that produce IL10 in response to MaR1 treatment." (PMID 37808700, 2024). "Celiac disease (C), also considered an autoimmune disease, includes an increased percentage of CD24hiCD38hi Bregs, as well as increased expression of CD1d on IL-10 secreting B cells under chronic intestinal inflammatory conditions." (PMID 38134245, 2024). "IL-10 is involved in a wide range of physiological and pathological processes, including autoimmune diseases, allergies, infections, and cancer." (PMID 38397895, 2024). "IL-10, a well-known anti-inflammatory cytokine, has been reported to have therapeutic effects in various inflammatory diseases such as autoimmune disease, tissue damage, cancer, chronic renal disease, and inflammatory bowel disease." (PMID 39052574, 2024). "This transition can be influenced by a vitamin D (calcitriol), favouring a shift towards Tr1 cells and increased IL-10 production, as described in some autoimmune diseases." (PMID 39403120, 2024). "Tregs, through the secretion of inhibitory cytokines such as transforming growth factor-β (TGF-β) and interleukin-10 (IL-10), modulate immune responses, dampen inflammatory reactions, and mitigate autoimmune diseases." (PMID 39064795, 2024). "IL-10-producing B cells have also been shown to be critical for preventing and controlling autoimmune disease and chronic inflammation." (PMID 37180165, 2023).
autoimmune disease (continued). "A principal function of Bhlhe40 in infectious and autoimmune disease models in mice is to suppress IL-10 expression in CD4+ T cells (17, –, 19, 22)." (PMID 37843306, 2023). "Polyvalent IgG can induce activation of Treg cells to produce IL-10 and exert a systemic immunomodulatory effect and clinical efficacy in patients with allergic and autoimmune diseases." (PMID 38094290, 2023). "On the other hand, aconite can inhibit the release of inflammatory cytokines, including IL-6, IL-8, and IL-10, in several autoimmune diseases." (PMID 36756040, 2023). "IL‐10 is a wide spectrum of anti‐inflammatory activity, and IL‐2 performs therapeutic ability in treating autoimmune diseases." (PMID 37506142, 2023). "In peripheral blood from both healthy individuals and patients with autoimmune diseases or neoplasms, various IL10 producing subtypes have been reported." (PMID 36973425, 2023). "Subsequently, this increases the endogenous IL-10 levels, allowing it to act as a pleiotropic immunostimulatory signaling molecule, such as that in autoimmune diseases and human cancers." (PMID 37161468, 2023). "IL-4 and IL-10 are key immunomodulatory cytokines that stimulate Th2 cell production while inhibiting Th1 response, hence limiting autoimmune disorders." (PMID 37893036, 2023). "Members of the IL-10 are also involved in host-pathogen interactions, wound healing, and have potential in the treatment of respirator, inflammatory and autoimmune diseases." (PMID 37484532, 2023). "Phenotypic assessment of the regulatory populations in autoimmune diseases led to the description of various subtypes with IL10- or TGFβ1-dependent suppressive mechanisms." (PMID 36973425, 2023). "In particular, a previous study proposed a T cell gene expression panel including the OAS2, CD70, and IL10 genes as useful biomarkers for SLE discrimination from other autoimmune diseases and for the monitoring of disease activity." (PMID 36428917, 2022). "IL-10 is essential for host defense against various infections and developing many autoimmune diseases." (PMID 36009467, 2022). "Although IL-10 has an anti-inflammatory effect that prevents inflammation as the main pathogenesis of autoimmune disorders, its role in modulating disease progression in T1D is debatable." (PMID 35725652, 2022). "IL-26 is a member of the IL-10 cytokine family and plays a key regulatory role in multiple chronic inflammations and autoimmune diseases." (PMID 35902909, 2022). "Increased frequencies of IL-10+ B cells and their progenitors were found in patients with various autoimmune diseases, such as SLE, RA, SS, autoimmune vesiculobullous skin disease, and MS." (PMID 35634292, 2022). "Further studies are needed to understand the regulation of IL-10 expression and function in different contexts with the aim of developing treatments for autoimmune diseases." (PMID 35869084, 2022). "Regulatory B cell subsets expressing IL-10 (B10 cells) modulate immune responses and the severity of autoimmune diseases." (PMID 35371051, 2022). "In this regard, IL-10 is an anti-inflammatory cytokine that plays a critical role in preventing the development of autoimmune diseases." (PMID 36443718, 2022). "Breg cells control autoimmune diseases by secreting anti-inflammatory cytokines (e. g., IL-10 and IL-35) and transforming growth factor-β." (PMID 35148758, 2022). "Administration of probiotics can modulate the action of DCs to produce IL-10 and IL-12 along with the expression of co-stimulatory molecules, and modify Th1/Th2 cytokine production in various autoimmune diseases." (PMID 35741032, 2022). "Accordingly, an imbalance between pro-inflammatory cytokine-producing B cells (mainly B cells producing IL-6) and IL-10-producing B cells has been described in multiple autoimmune diseases." (PMID 36179248, 2022). "Our studies incorporating IL-10 into sEVs of MSCs enhanced the advantages of both IL-10 and sEVs of MSCs in the inhibition of immune suppression in autoimmune diseases." (PMID 35255957, 2022).
autoimmune disease (continued). "The autoimmune diseases like Rheumatoid Arthritis (RA) have been widely classified as Th1 and Th17 disease and IL-10 expression is also found to be drastically reduced in these patients." (PMID 36238311, 2022). "SCFAs have been reported to promote the development of some autoimmune diseases, enhance interleukin-10 (IL-10) release, activate Treg cells, inhibit the production of proinflammatory cytokines, such as NF-kB, and alleviate colonic inflammation." (PMID 35650243, 2022). "These cells secrete IL-10 and inhibit Ab production by the B-cells, thus minimizing the chance of autoimmune disorders and graft (fetus) rejection." (PMID 35873599, 2022). "Tolerogenic dendritic cells (tolDC) inhibit antigen-specific proinflammatory T-cells, generate antigen-specific regulatory T-cells and promote IL-10 production in-vitro, providing an appealing immunotherapy to intervene in autoimmune disease progression." (PMID 36505460, 2022). "Treg cells directly or indirectly inhibit immune response and antibody production by expressing cellular receptors such as CTLA-4 or secreting cytokines such as TGF-β, IL-10, and IL-35, and are the therapeutic target of autoimmune diseases." (PMID 35983038, 2022). "IL-10, along with its receptors, plays an important role in the pathogenesis of various diseases, including infectious, inflammatory, and autoimmune diseases." (PMID 35300342, 2022). "CEBPD changes the Th17/Treg balance in an IL-10-dependent manner, and it plays a functional role in dendritic cells and central nervous system autoimmune diseases." (PMID 35204186, 2022). "As described in the context of autoimmune diseases, it will be interesting to investigate more in detail which B cell subsets contribute to the production of IL-10 during acute and chronic viral infections." (PMID 34293057, 2021). "Such a late increase agrees with expectations because IL-10 is well known to support resolution of inflammation and tissue repair and to protect from tissue damage in autoimmune diseases including lung damage as set out below." (PMID 33746948, 2021). "It is currently believed that IL-10 mainly acts on the feedback regulation stage of the immune pathway of patients with autoimmune diseases, and its serum levels are usually related to other proinflammatory cytokines." (PMID 34975721, 2021). "It has been reported that B cells from the autoimmune disease multiple sclerosis produce less of the anti-inflammatory cytokine IL-10." (PMID 34432649, 2021). "Collectively, even though only 1%–2% of splenic B cells are IL-10+ B cells, they play a critical role in the regulation of immune responses by suppressing immune responses and by ameliorating autoimmune diseases." (PMID 34108975, 2021). "As a pleiotropic cytokine, IL-10 have also been shown to promote inflammatory cytokine production in autoimmune diseases and cancers." (PMID 34251989, 2021). "The serum level of IL-10 in healthy adults is usually low, but it can be significantly elevated in patients with cancer or autoimmune diseases." (PMID 33708210, 2021). "The expression of IL-10 is altered in numerous human diseases including cancer, autoimmune diseases and inflammatory diseases." (PMID 34348761, 2021). "In that regard, IL-10 can be combined with AnnV to target self-reactive CD8 T cells that are responsible for tissue destruction in autoimmune disease." (PMID 34804041, 2021). "Last but not least, a regulatory subset of peripheral B cells, characterized by the ability to produce IL-10 upon ex vivo treatment with phorbol ester/ionomycin, is increased in adult autoimmune diseases." (PMID 33746948, 2021). "Previous studies confirmed the important role of IL-27 in the induction of IL-10-producing Tr1 cells to resolve autoimmune diseases, especially in EAE." (PMID 34299138, 2021). "Naïve IL-10+ B cells are involved in the prevention of immune responses in autoimmune diseases, while memory IL-10+ B cells prevent disease exacerbation." (PMID 34108975, 2021).
autoimmune disease (continued). "IL-20 is considered a proinflammatory factor in the context of autoimmune diseases; it also acts as an IL-10-related immunoregulatory molecule." (PMID 34122555, 2021). "IL-10 has the potential to treat cancer and human autoimmune diseases, such as inflammatory bowel disease (IBD) and rheumatoid arthritis." (PMID 33468130, 2021). "Interleukin-10 (IL-10) is an anti-inflammatory cytokine that plays an essential role in immune suppression and preventing various autoimmune diseases." (PMID 35474925, 2021). "The IL-10 produced by MCs is involved in the pathophysiology of contact dermatitis, autoimmune diseases, and immune privilege in the bladder." (PMID 34067047, 2021). "Changes in the levels of cytokines, especially TGF-β and IL-10, have been proved playing a key role in the self-regulation of many autoimmune diseases." (PMID 34975721, 2021). "Human IL-10+ B cells also express Tim-1, Tim-1+IL-10+ B cells are reported to suppress certain autoimmune diseases in human." (PMID 34108975, 2021). "Emerging evidence suggests a potent regulatory function of IL-35 and IL-10 in orchestrating autoreactive Breg cells responses and reveals significantly impaired IL-10/IL-35-producing capacity in Breg cells upon autoimmune disease progression." (PMID 34950136, 2021). "The utility of TIM-1 as a marker for a proportion of human IL-10+ Bregs has been further confirmed in inflammatory and autoimmune diseases, such as in RA patients, who exhibit reduced frequencies of TIM-1+ Bregs." (PMID 33995344, 2021). "defined a subset of Bregs named “B10 cells” whose anti-inflammatory potential is only attributable to the production of IL-10 cytokine in various disease models such as cancer, autoimmune diseases, and infectious diseases." (PMID 34276682, 2021). "Numerous clinical studies attempted to assess the efficacy of recombinant IL-10 in treating autoimmune diseases." (PMID 35053004, 2021). "As a key anti-inflammatory cytokine, IL-10 is crucial in preventing inflammatory and autoimmune diseases." (PMID 33572870, 2021). "Meanwhile, it was reported that IL-10-producing B cells inhibit autoimmune diseases by activating Tregs, thereby downregulating the production of proinflammatory cytokines." (PMID 32063984, 2020). "In autoimmune diseases, defective transitional B cells have impaired IL-10 production upon activation via the CD40." (PMID 32973780, 2020). "STAT3 mediated resistance to these CNS autoimmune diseases derives from inability to produce Th17 cells and promotion of exaggerated expansion in Foxp3-, IL-10-, IL-4-, and IFN-γ-expressing T cells." (PMID 33004854, 2020). "Functionally, Bregs can, through their secreting IL-10, inhibit inflammatory T cell responses in animal models of infection and autoimmune disease." (PMID 33072159, 2020). "The major biological function of IL-10 is to limit and stop the inflammatory response, which is pivotal in autoimmune diseases, inflammatory diseases and cancer." (PMID 32582189, 2020). "Replenishment of IL-10 secreting Breg cells through adoptive transfer reduced autoimmune disease severity in 15 week-old female MRL/lpr mice." (PMID 33240280, 2020). "As shown by recent studies, tolerogenic dendritic cells producing IL-10 induce tolerance via activation of Treg cells in murine models of autoimmune disease." (PMID 32318058, 2020). "CD19+CD24hiCD38hi B cells are immature transitional B cells that, in normal individuals, exert suppressive effects by IL-10 production but are quantitatively altered and/or functionally impaired in individuals with various autoimmune diseases." (PMID 32104147, 2020). "A previous study also found that IL-35 negatively regulated the development of autoimmune diseases by inducing the generation and expansion of IL-10-producing B cells." (PMID 32764544, 2020). "IL-10 is a pleiotropic cytokine mainly secreted by macrophages and plays crucial functions in the initiation of autoimmune diseases." (PMID 32063984, 2020).
autoimmune disease (continued). "In autoimmune diseases, the effects of IL-10 are only inhibitory; although, TGF-β can act synergistically with proinflammatory cytokines and even causes fibrotic lesions and promotes autoimmune pathologies." (PMID 32384594, 2020). "In autoimmune diseases, plasmablasts in the dLNs serve as IL-10 producers to limit autoimmune inflammation, while the absence of IL-10+ plasmablasts increases disease severity." (PMID 32973780, 2020). "IL-10 regulates a variety of immune cells to limit and stop the inflammatory response, and thus plays an important role in autoimmune diseases, inflammatory diseases and cancer." (PMID 32582189, 2020). "HIF-1α is a critical transcription factor for interleukin 10 (IL-10)-producing B cells in autoimmune diseases." (PMID 33003428, 2020). "In this light, one of its analogs, octreotide, whose binding activity is limited to SSR2 and 5, seems to be able to inhibit the production of TNFα and to increase the production of Interleukin-10 (IL-10) in patients with autoimmune diseases." (PMID 32766136, 2020). "The mechanism involved in the control of autoimmune diseases also involves the immunoregulatory property of elevating IL-10 expression and Treg signaling, attenuating the self-reactive T lymphocyte responses." (PMID 35047886, 2020). "IL-35 negatively regulated the development of autoimmune disease by inducing the generation and expansion of IL-10-producing B cells." (PMID 32764544, 2020). "The results of this study have improved our understanding of the post-transcriptional regulation of IL-10 in Bregs and provide a potential application for Bregs in the treatment of autoimmune diseases." (PMID 29844590, 2019). "Recent studies showed that the increase of IL-10-producing Foxp3+Tregs was accompanied with disease remission in several different systematic autoimmune diseases, such as experimental autoimmune encephalomyelitis, diabetes, and arthritis." (PMID 31380412, 2019). "Adoptive transfer of IL-10-secreting B cells inhibited the onset of chronic collagen-induced arthritis in mice, suggesting a major role for regulatory B cells in autoimmune diseases." (PMID 31683524, 2019). "Our finding is supported by additional studies showing that increased IL-10 production occurs in parasite-mediated amelioration of autoimmune diseases." (PMID 31888063, 2019). "IL-10-producing B cells are important in autoimmune diseases, as IL-10 is a proliferation factor for B cells and has well-known regulatory functions." (PMID 30761150, 2019). "One of the recent studies showed that IL-4 enhances IL-10 production by Th1 cells and ameliorate Th1 driven pathology in infectious, allergic, and autoimmune diseases." (PMID 31190704, 2019). "In particular, CD1dhiCD5+ B10 cells are functionally characterized by their ability to produce IL-10 to provide immune suppression in inflammatory and autoimmunity diseases." (PMID 31474988, 2019). "Administration of IL-10 to treat autoimmune diseases has been studied extensively and led to a reduction of psoriatic plaques in psoriasis and ameliorated the disease activity in intestinal bowel disease." (PMID 31036055, 2019). "Recently, there has been increasing evidence that IL-10 is involved in the development and progression of autoimmune diseases." (PMID 31240224, 2019). "IL-10 is also a well-known anti-inflammatory cytokine, with inhibitory effects on autoimmune disease." (PMID 30818368, 2019). "We also assessed the percentage of CD19+IL-10+ cells in the spleen, which are B10 cells that have emerged as an important cell type regulating diverse autoimmune disorders." (PMID 31311609, 2019).